ESAM (endothelial cell adhesion molecule)
Diseases named in the same sentence as ESAM in open-access papers:
ESAM is named in the same sentence as 39 diseases in open-access papers, as found by Europe PMC text mining. Sharing a sentence is not in itself a finding about the gene and the disease. The quoted sentences say what the papers report.
atherosclerosis (4 papers, 2011 to 2025). A disease characterized by the build-up of fatty material and calcium deposition in the arterial wall resulting in partial or complete occlusion of the arterial lumen. "LPA has pro-atherogenic effects on most of the cells involved in atherosclerosis, promoting vascular smooth muscle proliferation, endothelial cell adhesion molecule expression, and stimulating oxLDL uptake by macrophages." (PMID 25835000, 2015). "Cyclophilin A (CyPA; encoded by PPIA) is a ubiquitously expressed protein secreted in response to inflammatory stimuli that stimulates vascular SMC migration and proliferation, endothelial cell adhesion molecule expression, and inflammatory cell chemotaxis, thereby promoting atherosclerosis." (PMID 35637715, 2022). "In addition to these inflammatory mechanisms, the endothelial cell-selective adhesion molecule (ESAM), a member of the immunoglobulin superfamily, has been shown to play a pivotal role in atherosclerosis." (PMID 40419871, 2025).
endothelial dysfunction (4 papers, 2024 to 2025). In vascular diseases, endothelial dysfunction is a systemic pathological state of the endothelium (the inner lining of blood vessels) and can be broadly defined as an imbalance between vasodilating and vasoconstricting substances produced by (or acting on) the endothelium. "Their concentrations, particularly VCAM-1, ICAM-1, and ESAM, have been shown to be associated with endothelial dysfunction, vascular damage, and increased risk of atherosclerotic cardiovascular disease." (PMID 39234240, 2024). "The prothrombotic shift in infected lungs was revealed by increased expression of the coagulation cascade mediators TF, PLAT, PAI-1, THBD, and vWF associated with endothelial dysfunction as shown through the upregulated expression of ESAM, CD106, CD201, VEGF-A, and VEGFR-2." (PMID 38474396, 2024). "The elevated PVR observed in ESAM−/− mice is attributed to endothelial dysfunction, which occurs and persists independent from LV diastolic dysfunction." (PMID 39740345, 2025). "Pb and Cd exposure can reduce NO production by inhibiting eNOS, augment the secretion levels of endothelial cell adhesion molecule, eventually resulting in endothelial dysfunction and vascular injury." (PMID 40933415, 2025). "The targeted markers, ESAM, CD106, CD201, VEGF-A, and VEGFR-2, whose elevated expression is associated with inflammation and endothelial dysfunction were indeed upregulated at 4 dpi." (PMID 38474396, 2024).
Sepsis (4 papers, 2010 to 2023). Sepsis is defined as life-threatening organ dysfunction caused by a dysregulated host response to infection. "sepsis was associated with the C11_Plate cluster, and ESAM, HBG2, MMRN1, PF4V1, SAMD14, SELP, and TGFB1I1 may be important in this context." (PMID 37919720, 2023). "VCAM-1 is an inducible endothelial cell adhesion molecule that is scarcely expressed in resting endothelium and highly upregulated upon inflammatory stimulation during hemorrhagic shock and sepsis." (PMID 29763440, 2018). "In the GSE95233 control and sepsis groups, IFNGR1 (interferon gamma receptor 1), and ESAM (endothelial cell selective adhesion molecule) had degree 49 and 21, respectively." (PMID 33667236, 2021). "Similar to the hypo-inflammatory stage of sepsis, submaximal activation with 10 ng/ml still upregulated CD11b and downregulated L-selectin on PMN to the same degree as 100 ng/ml did, however, without having an effect on endothelial cell adhesion molecule expression." (PMID 21059228, 2010).
Obesity (3 papers, 2025). Accumulation of substantial excess body fat. "Furthermore, a subpopulation of CD206hiEndothelial cell adhesion molecule (ESAM)+ liver macrophages has been recently revealed to be metabolically responsive through the expression of CD36, which promotes oxidative stress associated with diet‐induced obesity and hepatic steatosis." (PMID 41163804, 2025).
anemia (2 papers, 2016 to 2019). A reduction in the number of red blood cells, the amount of hemoglobin, and/or the volume of packed red blood cells. "Furthermore, ESAM deficiency causes life-threatening myelosuppression, particularly severe anemia, in stress-induced hematopoiesis." (PMID 31813828, 2019). "However, it remains unclear what stage of erythropoiesis is impaired and what mechanisms are involved in the severe and prolonged anemia seen in ESAM-deficient mice after 5-FU treatment." (PMID 27111450, 2016). "Analyses of these fetuses showed that, as was the case in conventional ESAM-null mice, severe anemia occurred in approximately half of Cdh5-BAC-CreERT2·ESAMflox/flox fetuses." (PMID 31813828, 2019). "As a result, we found that some ESAM-null fetuses exhibited severe anemia after E15.5 and that approximately half of those anemic fetuses died before E17.5." (PMID 31813828, 2019). "Slight anemia was observed in ESAM-KO mice after PHZ administration in a trend consistent with that seen in the homeostatic condition." (PMID 27111450, 2016). "ESAM-KO mice experienced severe and prolonged anemia after 5-FU treatment compared to wild-type (WT) mice." (PMID 27111450, 2016). "Approximately half of ESAM-null fetuses died after mid-gestation due to anemia." (PMID 31813828, 2019). "Next, we examined if hemolysis or defective production of erythropoiesis-related molecules might be involved in the severe anemia seen in ESAM-KO mice after 5-FU treatment." (PMID 27111450, 2016). "ESAM-KO mice showed slight anemia, even under homeostatic conditions." (PMID 27111450, 2016). "Additionally, ESAM-KO mice experienced severe anemia after 5-FU treatment." (PMID 27111450, 2016). "The surviving ESAM-KO mice sharply recovered their WBC count and platelet levels after day 10, but their anemia was severe and prolonged in comparison to WT mice." (PMID 27111450, 2016). "The reason why not all the ESAM-null fetuses died would be explained by the heterogeneity of definitive HSCs, which might have buffered the life-threatening anemia." (PMID 31813828, 2019).
epilepsy (2 papers, 2024 to 2025). A brain disorder characterized by episodes of abnormally increased neuronal discharge resulting in transient episodes of sensory or motor neurological dysfunction, or psychic dysfunction. "As a consequence, JAM2, JAM3 (junctional adhesion molecule 2 and 3 [MIM: 606870 and 606871]), OCLN (occludin [MIM: 602876] and ESAM (endothelial cell adhesion molecule [MIM: 614281])dysfunction can present with overlapping clinical features showing severe developmental encephalopathies and epilepsy." (PMID 39414991, 2025).
malignant melanomas (2 papers, 2014 to 2024). "Further analysis identified the upregulation of VEGF, NOTCH, collagen, endothelial cell adhesion protein ESAM and activin pathways in rCap, while melanoma cells were found to communicate with all ECs." (PMID 39627185, 2024). "Finally, gene expression data analysis of primary malignant melanomas revealed a correlation between WNT5A expression and the angiogenesis marker ESAM." (PMID 24766647, 2014).
microcephaly (2 papers, 2024 to 2025). A congenital or acquired developmental disorder in which the circumference of the head is smaller than normal for the person's age and sex. "Hydrocephalus, failure to thrive, microcephaly, seizures, retinal anomalies and profound delay are being common features in ESAM deficient patients." (PMID 39414991, 2025).
acute respiratory distress syndrome (1 paper, 2022). Progressive and life-threatening pulmonary distress in the absence of an underlying pulmonary condition, usually following major trauma or surgery. "PECAM1, an endothelial cell adhesion molecule, played a potentially protective role in lung injury and acute respiratory distress syndrome." (PMID 36387401, 2022).
angiosarcoma (1 paper, 2013). A malignant tumor arising from the endothelial cells of the blood vessels. "In addition to including various vascular endothelial markers (ECSCR, TIE1, CD34, CDH5, ESAM), the angiosarcoma gene signature also included ROS1, supporting a possible broader role of ROS1 in the pathogenesis of this disease." (PMID 23637631, 2013).
cardiac hypertrophy (1 paper, 2023). "Since ESAM was shown to play a role in the angiogenic process, it is possible that an excessively cleaved or dysfunctional ESAM results in an impaired angiogenic response, and as cardiac hypertrophy progresses this could lead to LV diastolic dysfunction." (PMID 36946064, 2023).
endometrial cancer (1 paper, 2025). Primary or metastatic malignant neoplasm involving the endometrium (mucous membrane that lines the endometrial cavity). "In endometrial cancer, a spatially separated vascular CAFs subgroup characterized by high levels of MYH11, ESAM, MCAM, and EPAS1 was a poor prognostic factor for patients with endometrial cancer." (PMID 39764562, 2025).
Hypercholesterolemia (1 paper, 2023). An increased concentration of cholesterol in the blood. "Thus, in the setting of hypercholesterolemia, endothelial cell adhesion molecule expression and leukocyte-endothelial cell adhesion are promoted by macrophage cyp27a1." (PMID 37491347, 2023).
intracranial hemorrhage (1 paper, 2025). Bleeding within the SKULL, including hemorrhages in the brain and the three membranes of MENINGES. "Bi-allelic loss-of-function variants in ESAM are assigned to a disease termed neurodevelopmental disorder with intracranial hemorrhage, seizures, and spasticity (NEDIHSS) (OMIM# 620371)." (PMID 39414991, 2025). "However, intracranial hemorrhage (ICH) seems very characteristic to JAM3- and ESAM-related phenotypes whereas bilateral generalized polymicrogyria and band like calcification are universal in OCLN." (PMID 39414991, 2025).
ovarian carcinoma (1 paper, 2013). A malignant neoplasm originating from the surface ovarian epithelium. "Cluster of differentiation 146 (CD146) is an endothelial cell adhesion molecule which is overexpressed in various types of malignant cancer, including ovarian cancer." (PMID 23599761, 2013).
Pancytopenia (1 paper, 2016). An abnormal reduction in numbers of all blood cell types (red blood cells, white blood cells, and platelets). "Once again, we confirmed that ESAM deficiency caused severe pancytopenia." (PMID 27111450, 2016). "We have previously reported that ESAM-KO mice exhibit a more life-threatening pancytopenia than WT mice within 10 days after a single 5-FU injection." (PMID 27111450, 2016).
psoriasis (1 paper, 2025). An autoimmune condition characterized by red, well-delineated plaques with silvery scales that are usually on the extensor surfaces and scalp. "Furthermore, the potential mediating roles of ESAM and IL-16 in psoriasis-induced AMI susceptibility are yet to be explored in depth." (PMID 40419871, 2025). "A total of 8 SNPs were correlated with psoriasis, 3 SNPs were correlated with ESAM, and 3 SNPs were correlated with IL-16, as identified at a genome-wide significance level of P < 5 × 10−8." (PMID 40419871, 2025). "Genetic liability to psoriasis is correlated with a higher risk of AMI, which is partially mediated by ESAM and IL-16." (PMID 40419871, 2025). "The proportion of the effects of genetically-predicted psoriasis mediated by genetically-predicted ESAM, IL-16, and both ESAM and IL-16 was estimated as 24.8% (95% CI: 8.3%–41.2%), 16.1% (95% CI: 5.3%–26.8%), and 26.9% (95% CI: 6.3%–47.6%), respectively." (PMID 40419871, 2025). "The proportion of the effecs of genetically-predicted psoriasis mediated by genetically-predicted ESAM was 24.8% (95% CI 8.3–41.2%)." (PMID 40419871, 2025). "The genetic liability to psoriasis (odds ratio [OR]: 1.00078; 95% confidence interval [CI]: 1.00008–1.00148; P = .028479), ESAM (OR: 1.00208; 95% CI: 1.00019–1.00397; P = .031089), and IL-16 (OR: 1.00118; 95% CI: 1.00009–1.00227; P = .033826) were associated with higher AMI risks." (PMID 40419871, 2025). "MR mediation analysis was used to determine whether ESAM and IL-16 mediate the effect of psoriasis on AMI." (PMID 40419871, 2025). "Additionally, ESAM and IL-16 play an intermediary role in psoriasis complicated with AMI." (PMID 40419871, 2025).
pulmonary edema (1 paper, 2023). Accumulation of fluid in the lung tissues causing disturbance of the gas exchange that may lead to respiratory failure. "Notably, ESAM−/− mice with UNX‐Aldo also developed pulmonary edema, when compared to wild type mice with UNX‐Aldo." (PMID 36946064, 2023). "When compared to wild types, ESAM−/− mice with UNX‐Aldo displayed worsening of LV diastolic function, as indicated by increased IVRT and pulmonary edema." (PMID 36946064, 2023).
renal failure (1 paper, 2024). "Another study, based on the SOMAscan proteomics platform, screened three proteins (Delta-like 1, endothelial cell adhesion molecule, and mitogen-activated protein kinase 11) as candidate biomarkers for predicting the risk of DKD progression to renal failure." (PMID 38481996, 2024).
schizophrenia (1 paper, 2022). A major psychotic disorder characterized by abnormalities in the perception or expression of reality. "A genome-wide association study found that six immune candidates, namely, DPP4, HSPD1, EGR1, CLU, ESAM, and NFATC3, were associated with schizophrenia." (PMID 35757702, 2022).
tumor (15 papers, 2012 to 2025). "VEGF has been shown to suppress the activation of tumor-associated endothelial cells and downregulate endothelial cell-selective adhesion molecule (ESAM), a key mediator of leukocyte adhesion and transendothelial migration." (PMID 41278271, 2025). "Studies have found that in mice with genetic ESAM deletion, tumor vascularization and tumor growth are reduced." (PMID 36946064, 2023). "ESAM has been suggested to have a special functional role in pathological angiogenic processes such as tumour growth." (PMID 32095334, 2020). "We assessed the platelet and endothelial cell adhesion molecule (PECAM)-1-positive vascular surface area in each tumor using an image analyzer." (PMID 29707135, 2018). "We found that dietary treatment with PEITC significantly inhibited tumor platelet/endothelial cell adhesion molecule (PECAM-1/CD31) expression, a marker of angiogenesis." (PMID 22266918, 2012). "It has been proven that tumor growth in ESAM knockout mice is retarded." (PMID 35406725, 2022). "ESAM, a regulatory tight junction protein, was upregulated in tumor LECs." (PMID 36067135, 2022). "Indeed, we observed significantly lower concentrations of ESAM, a protein specific to endothelial cells, compared to matched, non-tumor tissue." (PMID 22509397, 2012). "For Fra-2 cl 2 primary tumours, genes such as SRGN (Serglycin) and ESAM were upregulated, while CD99 and SELPLG (selectin P ligand) were downregulated." (PMID 34693476, 2022). "We also measured the vessel density by using the platelet endothelial cell adhesion molecule CD31, which was found to have a major role in the tumor microenvironment vessels." (PMID 35887515, 2022). "Cancer cells in solid areas discard tumor-suppressive adhesion interactions such as CDH1, CADM1, and ESAM with normal epithelial cells in comparison with those in the GG areas." (PMID 35874770, 2022). "Neither tumor endothelial cell adhesion molecule expression nor homing of activated T cells was affected by FUS+MBs." (PMID 32754281, 2020). "By immunohistochemical staining, we could confirm some of these gene products like MTA2, ESAM, and LGALS1 in primary tumour and in metastasized cells in the lung of the two clones, but CTTN only in primary tumour sections not in metastatic cells of the lung." (PMID 34693476, 2022).
cancer (8 papers, 2004 to 2025). A tumor composed of atypical neoplastic, often pleomorphic cells that invade other tissues. "ESAM is functionally important for hematopoiesis because ESAM deficiency causes severe BM suppression after administration of the anti-cancer drug, 5-fluorouracil (5-FU)." (PMID 27111450, 2016). "VCAM-1 is an endothelial cell adhesion molecule, which is shown to be involved in inflammation and cancer." (PMID 37179352, 2023). "For example, MAD2L2 and LRRC61 are risk factors in most cancers, while PFKFB3, ESAM, SYNM, and LRFN5 act as protective factors in most cancers." (PMID 38124743, 2023). "Furthermore, miR-7 diminishes the metastatic capacity of cancer stem cells (CSCs) via targeting RELA to suppress the production of endothelial-cell-selective adhesion molecule (ESAM)." (PMID 40710326, 2025). "Among O-linked carbohydrate antigens, sialyl LewisX has been reported to function as a ligand of the endothelial cell adhesion molecule E-selectin (ELAM-1), which adheres human cancer cells to the vascular endothelium." (PMID 14735190, 2004).
infection (3 papers, 2011 to 2025). The state of being infected such as from the introduction of a foreign agent such as serum, vaccine, antigenic substance or organism. "We found that the expression of ESAM, CD106, CD201, VEGF-A, and VEGFR-2 was significantly upregulated in correlation with the course of infection peak and modulations of ACE2, CD147, and GRP78 expression levels." (PMID 38474396, 2024). "Endothelial cell adhesion molecule (ICAM-1, VCAM, E- and P-selectin) expression in brain tissue on day 6 of infection was assessed in both groups by western blot." (PMID 21649904, 2011).
cardiovascular disease (2 papers, 2023 to 2025). "Of clinical importance, elevated serum levels of ESAM have been evaluated in cardiovascular diseases." (PMID 36946064, 2023). "Notable, in the Dallas Heart Study (involving 2,442 participants without prior cardiovascular disease) only soluble ESAM, but not soluble ICAM-1 or soluble VCAM-1, levels were associated with incidents of atherosclerotic and total cardiovascular disease." (PMID 39740345, 2025). "Notable, in the Dallas Heart Study, involving 2442 participants without prior cardiovascular disease soluble ESAM, but not soluble ICAM‐1 or soluble VCAM‐1, levels were associated with incident atherosclerotic and total cardiovascular disease." (PMID 36946064, 2023).
vasculopathy (1 paper, 2022). "Considering the intense inflammatory response induced by Aβ, it is expected that the upregulation of JAM-A (F11r) and ESAM is associated with leukocyte transmigration in CAA vasculopathy." (PMID 35813502, 2022).
ESAM also shares sentences with these, for which no sentence is quoted: arteriovenous malformation (1 paper); Failure to thrive (1); Hepatic steatosis (1); Hydrocephalus (1); inflammation (1); Intraventricular hemorrhage (1); mesothelioma (1); neurodevelopmental disorder (1); pulmonary arterial hypertension (1); pulmonary hypertension (1); steatosis (1); Subdural hemorrhage (1); thrombosis (1); type 2 diabetes (1).